DNMT3A (DNA methyltransferase 3 alpha)
Diseases named in the same sentence as DNMT3A in open-access papers (continued):
Sharing a sentence is not in itself a finding about the gene and the disease.
overgrowth syndrome (25 papers, 2015 to 2026). A group of syndromes caused by genetic birth defects that may lead to the development of malignancies. "The role of DNMT3A in physiological growth was first identified by an array of patients exhibiting overgrowth syndrome with de novo germline missense and truncating loss-of-function variants." (PMID 37303757, 2023). "DNMT3A overgrowth syndrome (DOS), caused by germline pathogenic variants in the DNA methyltransferase gene DNMT3A, has been associated with a predisposition toward development of hematopoietic and neuronal malignancies." (PMID 37160317, 2023). "Although DNMT3A variants have been associated with an overgrowth syndrome, the major clinical features of TBRS are overgrowth (either in tall stature or macrocephaly, 2 SDs above population mean) and intellectual disability." (PMID 37303757, 2023). "Through whole-genome sequencing, DNMT3A has been identified as a candidate gene marker for autism spectrum disorder, and mutations in DNMT3A have been involved in overgrowth syndrome and acute monocytic leukemia." (PMID 33649938, 2021). "Germline mutations in the DNMT3A gene can cause an overgrowth syndrome associated with behavioural and hematopoietic phenotypes." (PMID 34315901, 2021). "In particular, missense mutations in arginine at position 882 causing a change either to cysteine or histidine (a change seen in about half of the cases of AML with a mutation in DNMT3A) were also documented in affected patients with the overgrowth syndrome." (PMID 33194904, 2020). "Given that previously known mutations in DNMT3A causing overgrowth syndrome result in genome-wide hypomethylation, the PWWP mutation in PCC/PGL leading to hypermethylation is described as gain-of-function mutation." (PMID 31091831, 2019). "More recently, mutations DNMT3A, another DNA methyltransferase involved in the de novo methylation of DNA were also identified in patients with overgrowth syndromes." (PMID 27834868, 2016). "Besides, specific heterozygous mutations of DNMT3A has been linked to DNMT3A overgrowth syndrome or Tatton-Brown Rahman syndrome (TBRS; OMIM 615879), an NDD characterized by IDD, overgrowth, craniofacial abnormalities, anxiety, and ASD." (PMID 40469903, 2025). "Loss-of-function mutations in DNMT3A, a DNA methyltransferase, or NSD1, a histone methyltransferase, cause overgrowth syndromes." (PMID 41456056, 2025). "Tatton-Brown–Rahman syndrome (TBRS), also known as DNMT3A overgrowth syndrome, was first characterized by Tatton-Brown and colleagues in 2014 following the identification of the DNMT3A gene." (PMID 39902084, 2024). "Several studies have tried to characterize crosstalk between NSD1, PRC2, and DNMT3A in an attempt to mechanistically unify these overgrowth syndromes." (PMID 38370361, 2024). "In this report, we describe DNA methylation alterations and their consequences in human patients, and a mouse model of the DNMT3A Overgrowth Syndrome (DOS)." (PMID 34315901, 2021). "Another autosomal dominant overgrowth and intellectual disability (OGID) syndrome, similar to Sotos and Weaver syndromes, is a DNMT3A-related overgrowth syndrome, also known as Tatton–Brown–Rahman syndrome (OMIM 615879)." (PMID 33194904, 2020). "Tatton-Brown-Rahman syndrome (TBRS; OMIM 615879), also known as the DNMT3A-overgrowth syndrome, is an overgrowth intellectual disability syndrome first described in 2014 with a report of 13 individuals with constitutive heterozygousDNMT3A variants." (PMID 29900417, 2018). "Tatton-Brown-Rahman syndrome (TBRS;OMIM 615879), also known as the DNMT3A-overgrowth syndrome, is an overgrowth intellectual disability (OGID) syndrome first described in 2014 with a report of 13 individuals withde novo heterozygousDNMT3A variants." (PMID 29900417, 2018). "Consistent with this idea, mutations in the DNA methyltransferase gene DNMT3A, SETD2 and EZH2 have also been shown to cause overgrowth syndromes." (PMID 27688808, 2016).
overgrowth syndrome (continued). "Finally, it is important to note that mutations in DNMT3A have been found to cause an overgrowth and intellectual disability syndrome referred to as Tatton–Brown–Rahman syndrome (TBRS) or DNMT3A overgrowth syndrome." (PMID 37947606, 2023). "Our patient’s stop-gain mutation in DNMT3A was previously reported in an overgrowth syndrome with intellectual disability, but he did not exhibit the phenotype described by the authors." (PMID 34796114, 2021). "Unlike in AML and MDS, most mutations in overgrowth syndrome do not directly affect the catalytic activity of DNMT3A, but interfere with domain–domain interactions and histone binding, which further affect the activity of DNMT3A." (PMID 27446199, 2016).
atherosclerosis (23 papers, 2020 to 2025). A disease characterized by the build-up of fatty material and calcium deposition in the arterial wall resulting in partial or complete occlusion of the arterial lumen. "In DNMT3A-mutated macrophages, this impairment exacerbates lipid retention and inflammatory responses, accelerating the progression of atherosclerosis." (PMID 40244103, 2025). "Preclinical studies have shown that macrophages deficient in TET2 or DNMT3A drive interleukin (IL)-1β/IL-6 inflammasome activation, thereby promoting atherosclerosis and metabolic dysfunction, whereas the JAK2V617F mutation accelerates thrombosis." (PMID 41516113, 2025). "Experimental atherosclerosis was increased in females with Tet2 and males with Jak2, but it was unchanged with Dnmt3a mutations." (PMID 41433101, 2025). "The contributions of DNMT3A to cardiovascular risk require further study, especially in regard to disease processes beyond atherosclerosis, such as cardiac fibrosis and heart failure." (PMID 39352379, 2024). "In humans, CHIP due to DNMT3A shows a weaker association with atherosclerosis than TET2." (PMID 39352379, 2024). "Generally, DNMT3A mutations are most commonly seen in atherosclerosis and myeloid leukemia." (PMID 36387074, 2022). "Studies in the cardiovascular system have found that inhibiting Dnmt3a expression in bone marrow cells can lead to an increase in inflammation and the severity of atherosclerosis in mice." (PMID 39268349, 2024). "The causal effect of both DNMT3A and TET2 loss-of-function within myeloid cells upon clonal expansion and the development of atherosclerosis has also been demonstrated unequivocally in atherosclerosis-prone mice." (PMID 37304954, 2023). "In this context, somatic mutations, particularly in DNA methyltransferase 3 alpha and TET methylcytosine dioxygenase 2, are also implicated in the pathogenesis of both atherosclerosis and DKD, partly by a pro-inflammatory effect." (PMID 36983082, 2023). "In contrast to DNMT3a, the overexpression of Dnmt1 promotes proinflammatory cytokine production in macrophages and plasma during atherosclerosis and inflammation." (PMID 37929702, 2023). "DNMT1 and DNMT3a are two major DNMTs in ECs that direct the methylation of genes or signaling molecules to modulate aortic disorders, such as atherosclerosis." (PMID 36293392, 2022). "Somatic mutations of DNMT3A and TET2 were also associated with accelerated atherosclerosis, thus increasing the risk of cardiovascular disease mediated by inflammatory mechanisms." (PMID 32457355, 2020). "Therefore, DNMT3A mutations, similar to TET2 and JAK2, link epigenetic regulation of autophagy to macrophage-driven atherosclerosis." (PMID 40244103, 2025). "Interestingly, Dnmt3a LOF augmented atherosclerosis only when homozygous, in contrast with findings with Tet2 LOF." (PMID 39352379, 2024). "Despite different methylation patterns, TET2 or DNMT3A CHIP may both drive atherosclerosis by boosting inflammation." (PMID 39352379, 2024). "Mutations in DNMT3A and TET2 account for approximately 50% of CHIP mutations in people with atherosclerosis, with somatic DNMT3A mutations accounting for roughly 35% of mutations in patients with CHIP and coronary artery disease and early-onset myocardial infarction." (PMID 37947606, 2023). "Mutations in genes such as ten-eleven translocation-2 (TET2), Janus kinase 2 (JAK2), and DNA methyltransferase 3 alpha (DNMT3A), which are frequently observed in patients with CH, have been shown to promote inflammatory responses and alter macrophage function in the context of atherosclerosis." (PMID 40244103, 2025). "In summary, atherosclerosis and CHIP form a self-perpetuating cycle in which inflammation drives HSC proliferation and mutation accumulation, while mutant clones, particularly those with TET2 and DNMT3A alterations, boost pro-inflammatory signaling and accelerate vascular dysregulation." (PMID 41516113, 2025).
atherosclerosis (continued). "While other CHIP driver mutations, including TET2, associate with adverse cardiovascular outcomes among individuals with prevalent atherosclerosis, DNMT3A seems not to confer the same risk, although some studies did show a weak association with elevated incident coronary heart disease." (PMID 39352379, 2024). "In contrast to TET2 and DNMT3A, where NLRP3 inflammasome activation appears predominant as a mechanism that drives accelerated atherosclerosis, recent data suggest that ASXL1 and JAK2 CHIP provoke activation of the AIM2 inflammasome." (PMID 39352379, 2024). "If the relationship of DNMT3a mutations with increased cardiovascular risk in CKD patients is confirmed in larger studies, it could suggest the existence of new specific mechanisms for the progression of the disease, atherosclerosis in patients with nephropathies, and new therapeutic alternatives." (PMID 37763205, 2023).
T-cell lymphomas (23 papers, 2013 to 2025). "The data suggest that TET2/DNMT3A mutations were present in many types of human malignancies and frequent in T cell lymphomas, chronic myelomonocytic leukemia and AML." (PMID 34039392, 2021). "While well known to be mutated in myeloid malignancies, DNMT3A is additionally mutated in roughly 30% of nodal T-cell lymphomas." (PMID 33801781, 2021). "It is conceivable that certain TET2 or DNMT3A mutations are stronger drivers that can result in more expanded CH and/or higher efficient T-cell lymphoma development." (PMID 34581268, 2021). "TET2 and NPM1 mutations are markedly associated with DNMT3A mutations in T-cell lymphoma and adult AML, respectively." (PMID 23946816, 2013). "This region overlaps with the majority of the DNMT3A, a gene commonly mutated in T-cell lymphoma and myeloid leukemia." (PMID 23533652, 2013). "DNMT3A is the most frequently mutated gene in myeloid and T-cell lymphomas." (PMID 33160401, 2020). "Genetic mutations, including DNMT3A and TET2, involved in clonal hematopoiesis, have been identified in both DLBCL and secondary T cell lymphoma." (PMID 41117994, 2025). "This case provided evidence for a divergent evolution of two clonally-unrelated T-cell lymphomas (cPTCL-NOS and AITL) originating from a common progenitor, which shared the same mutations in TET2 and DNMT3A." (PMID 37646869, 2023). "It is believed that DNMT3A mutations arise in hematopoietic progenitor stem cells, upstream of T-cell lineage commitment based on the observation of identical DNMT3A and TET2 mutations in tumor and normal cells in T-cell lymphoma patients." (PMID 33801781, 2021). "We show that 43% of Dnmt3b+/− mice developed T-cell lymphomas, chronic lymphocytic leukemia, and myeloproliferation over 18 months, thus resembling phenotypes previously observed in Dnmt3a+/− mice, possibly through regulation of shared target genes." (PMID 33450231, 2021). "In a study of human T-cell lymphoma, simultaneous mutation of TET2 and DNMT3A was detected and DNMT3A mutation precedes TET2 mutation." (PMID 27183914, 2016). "Altogether, these data suggest that Dnmt3a is a haploinsufficient tumor suppressor gene in the prevention of CD8+ T cell lymphomas and CLL in mice." (PMID 27690235, 2016). "Similarly to our previous study of Dnmt3a+/− mice, our data identify Dnmt3b as a haploinsufficient tumor suppressor in T-cell lymphomas (TCL) and CLL." (PMID 33450231, 2021). "In addition, DNMT3A and TET2 mutations occur concurrently in human malignancies such as T cell lymphoma." (PMID 34039392, 2021). "Interestingly, it has been observed that phenotypically unrelated cancers such as T cell lymphomas of the angioimmunoblastic subtype and MPNs share some genetic markers such as TET2 and DNMT3a mutations that are usually considered myeloid." (PMID 33092233, 2020). "It indicated the role of DNMT3A in T-cell lymphoma at early stage." (PMID 27183914, 2016). "Thus, consistent with heterozygous mutations of Dnmt3a found in human T cell malignancies, Dnmt3a is a haploinsufficient tumor suppressor gene in the prevention of mouse mature CD8+CD4- T cell lymphomas." (PMID 27690235, 2016). "In addition, Dnmt1 was shown to have cancer-specific de novo activity in a mouse model of MYC-induced T cell lymphomas, whereas Dnmt3a and Dnmt3b were primarily involved in maintenance methylation in tumors." (PMID 27690235, 2016). "Similarly, hypomethylating agents have been explored in T-cell lymphomas with a TFH phenotype given the known efficacy of this mechanism in myeloid disorders enriched for mutations in TET2 and DNMT3A, mutations that are similarly frequent in T-cell lymphomas with a TFH phenotype." (PMID 36765544, 2023).
T-cell lymphomas (continued). "The T-cell lymphoma panel showed no mutations in RHOA, TET2, DNMT3A, IDH2, and other genes typically altered in TFH-derived and other T-cell lymphomas in both lymph node and BM specimens, further supporting the diagnosis of NMZL." (PMID 41515931, 2025). "In particular, in our previous studies we observed upregulation of Dnmt3b in Dnmt3a-defficient MYC-induced T cell lymphomas, suggesting that such an event may result in aberrant de novo methylation." (PMID 27690235, 2016).
Insulin resistance (22 papers, 2017 to 2025). Increased resistance towards insulin, that is, diminished effectiveness of insulin in reducing blood glucose levels. "Additionally, we tested whether the causal role of Dnmt3a in the development of insulin resistance is conserved in human adipocytes." (PMID 29091029, 2017). "The DNA methyltransferase DNMT3A mediates adipose insulin resistance through its downstream target gene Fgf21, a gene known to enhance glucose uptake and insulin sensitivity." (PMID 40862085, 2025). "RG108 and Azacitidine treatment can relief the DNMT3a-mediated insulin resistance through Fgf21 upregulation." (PMID 35216415, 2022). "It has been shown that DNA methylation at the Fgf21 locus was increased in human DM subjects, which is mediated by Dnmt3a and ultimately lead to insulin resistance." (PMID 34349728, 2021). "These researchers also found that adipose-specific Dnmt3a knockout in mice protected the animals from diet-induced insulin resistance and glucose tolerance." (PMID 31896238, 2019). "In cultured mouse and human adipocytes, Dnmt3a was reported to be both necessary and sufficient to mediate diet-induced insulin resistance." (PMID 31849831, 2019). "Adipose DNA methyltransferase 3a (Dnmt3a) was reported to be a novel epigenetic mediator of insulin resistance in vitro and in vivo." (PMID 31849831, 2019). "They found that Dnmt3a mediates insulin resistance by methylating the Fgf21 promoter; FGF21 hypermethylation was evident in human subjects with T2D and correlated negatively with FGF21 expression in human adipose tissue." (PMID 31896238, 2019). "Fgf21, a key negatively regulated Dnmt3a target gene, can rescue Dnmt3a-mediated insulin resistance." (PMID 31849831, 2019). "When the researchers knocked down or inhibited Dnmt3a, the fat cells were able to take up more glucose in response to insulin, even when they had been treated with substances that induce insulin resistance." (PMID 29239299, 2017). "Taken together, our data demonstrate that adipose Dnmt3a is a novel epigenetic mediator of insulin resistance in vitro and in vivo." (PMID 29091029, 2017). "Consistent with this, Fgf21 can rescue Dnmt3a-mediated insulin resistance, and DNA methylation at the FGF21 locus was elevated in human subjects with diabetes and correlated negatively with expression of FGF21 in human adipose tissue." (PMID 29091029, 2017). "Here, we demonstrate that DNA methyltransferase 3a (Dnmt3a) is both necessary and sufficient to mediate insulin resistance in cultured mouse and human adipocytes." (PMID 29091029, 2017). "In addition, someone discovered that deletion of DNMT3A specifically in the adipose tissue of mice protects from DNMT3A-induced insulin resistance." (PMID 40918255, 2025). "Further, adipo-specific DNMT3A-KO mice were protected from diet-induced insulin resistance and glucose intolerance, adipocyte Fgf21 was identified as a target gene inhibited by DNMT3A, and intriguingly, DNA methylation at the Fgf21 gene was elevated in adipose tissue of diabetic patients." (PMID 33235221, 2020). "Dnmt3a has recently been shown to be an epigenetic regulator of insulin resistance." (PMID 32092075, 2020). "Expression of endogenous FGF21 is decreased by Dnmt3a-mediated DNA methylation at the Fgf21 promoter, while exogenous FGF21 can restore Dnmt3a overexpression-induced insulin resistance." (PMID 34349728, 2021). "Mice with adipose-specific deletion of Dnmt3a are guarded against diet-induced insulin resistance through upregulated fgf21 expression, indicating that FGF21, as a crucial regulator, is affected by Dnmt3a in adipocytes." (PMID 34968255, 2021). "Dnmt3a knockout mice were protected from diet-induced insulin resistance without changes in adiposity." (PMID 40862085, 2025). "Adipose-specific Dnmt3a knock-out mice were reported to be protected from diet-induced insulin resistance and glucose intolerance without accompanying changes in adiposity." (PMID 31849831, 2019).
Insulin resistance (continued). "Furthermore, adipose-specific Dnmt3a knock-out mice are protected from diet-induced insulin resistance and glucose intolerance without accompanying changes in adiposity." (PMID 29091029, 2017).